CRH (corticotropin releasing hormone)
Diseases named in the same sentence as CRH in open-access papers (continued):
Sharing a sentence is not in itself a finding about the gene and the disease.
psoriasis (17 papers, 2015 to 2026). An autoimmune condition characterized by red, well-delineated plaques with silvery scales that are usually on the extensor surfaces and scalp. "Thus, they suggested that defective downstream immunosuppressive signaling, including CRH and GC, underlies the development of inflammatory skin conditions including psoriasis." (PMID 39108766, 2024). "Additionally, increased CRH production has been associated with the development of depressive symptoms, further underscoring the bidirectional relationship between stress, inflammation, and psychiatric comorbidities in psoriasis." (PMID 40428224, 2025). "In response to stress, CRH stimulates the production of proinflammatory cytokines within the skin, subsequently activating keratinocytes and promoting the formation of psoriasis plaques." (PMID 40428224, 2025). "TNF-α and IFN cytokines involved in psoriasis pathogenesis increase the levels of CRH as well as of adrenocorticotropic hormone (ACTH) and cortisol, which indicate the influence of inflammation on hormonal status in these patients." (PMID 38399624, 2024). "It has been shown that the levels of corticotropin-releasing hormone (CRH) in the skin of patients with psoriasis are higher compared to healthy skin." (PMID 38399624, 2024). "The elevation of CRH seen in the context of chronic stress is interesting from the pathophysiologic view of psoriasis." (PMID 33984200, 2022). "Biopsies from patients with psoriasis show a significant increase in CRH expression compared to healthy skin." (PMID 35054853, 2022). "The HPA axis is involved in the development of psoriasis by the release of CRH, ACTH, and glucocorticoids, and these regulate the skin response to stress and the topical immune response." (PMID 36405690, 2022). "MCs express CRHR1 in proximity of psoriatic plaques, and elevated CRH in psoriasis induces the degranulation of MCs." (PMID 36405690, 2022). "Consequently, the study proposes that the CRH/CRH-R1 system warrants further investigation as a potential target for new therapeutic strategies in treating psoriasis." (PMID 40650250, 2025). "CRH induces degranulation of mast cells along with increases in vascular permeability and expression vascular endothelial growth factor, the features of psoriasis." (PMID 40861201, 2025). "Additionally, CRH activates the pro-inflammatory nuclear factor kappa-B (NF-κB) pathway, which is a major part of the inflammatory response in psoriasis." (PMID 39108766, 2024). "This corresponds to the observation that both atopic dermatitis and psoriasis patients, whose skin lesions can be aggravated by psychoemotional stress, have increased serum CRH levels and that CRH protein expression and CRH-R1 transcription are increased in psoriatic skin lesions." (PMID 33803422, 2021). "Through all of these changes, CRH effectively shifts keratinocytes into an immunoactive state and thus may contribute to inflammatory skin conditions, such as psoriasis." (PMID 26550011, 2015). "We review existing studies examining the role of psychological or psychosocial stress at the molecular level in AD and psoriasis, highlighting the role of the HPA axis and IL-18 in AD, CRH and BDNF in psoriasis, and cortisol levels in both." (PMID 35572606, 2022). "The corticotropin-releasing hormone (CRH) is overexpressed in areas of inflammation, as well as in peripheral tissues including the skin, thus its dysregulation is an important factor in psoriasis pathogenesis." (PMID 35955731, 2022). "Psoriasis episodes are often preceded by stressful decreased expression of CRHR-1 which was observed in psoriatic epidermis or dermis, whereas increased levels of CRH were found in the serum of patients with psoriasis." (PMID 34513851, 2021).
adenoma (15 papers, 2013 to 2025). A neoplasm arising from the epithelium. "As regards ACTH synthesis, we did not observe differences in POMC expression between male- and female-excised adenomas both in unchallenged wells and after CRH/dexamethasone incubation." (PMID 32183012, 2020). "In fact, POMC increased from 20 to 500 % over baseline during CRH stimulation, even up to 14-fold in one adenoma." (PMID 27220856, 2017). "USP8-mutated corticotrope adenoma cells are more sensitive to corticotrope modulators, namely CRH and dexamethasone, in vitro, compared to USP8-wild-type (WT) ACTH-secreting adenomas, with higher levels of CRH and glucocorticoid (NR3C1) receptors." (PMID 35743266, 2022). "As shown in a different study, simultaneously CRH stimulation may improve the detection rate of adenomas by FDG-PET." (PMID 32743767, 2020). "Furthermore, corticotrope adenomas from males secreted less ACTH in response to CRH stimulation compared to females, although the percent change from baseline was comparable between sexes." (PMID 32183012, 2020). "Fifty-three ACTH-secreting adenomas were incubated with 10 nM CRH or 10 nM dexamethasone for 24 h." (PMID 27220856, 2017). "Therefore, bilateral inferior petrosal sinus sampling (BIPSS) with CRH stimulation was performed to obtain an accurate preoperative localization of the adenoma: the interpetrosal sinus ACTH gradient indicated lateralization of ACTH secretion to the left side." (PMID 25386368, 2014). "Finally, in the AtT-20 adenoma cells the CRH-directed complex was far superior to other ligands as would be expected from pituitary corticotroph cells." (PMID 23638840, 2013). "Similarly, functional imaging may improve the identification of ACTH-secreting adenomas noninvasively; Gallium-68-tagged corticotropin-releasing hormone (CRH) combined with PET-CT can be used to detect CRH receptors, which are upregulated on corticotroph adenomas." (PMID 37560300, 2023). "A well-established strategy is to waive BIPSS among those patients with adenoma over 6 mm on MRI plus concordant HDDST and CRH stimulation test." (PMID 34539574, 2021). "Adenomas were established in culture and ACTH synthesis and secretion assessed in basal conditions as well as during incubation with CRH or dexamethasone." (PMID 32183012, 2020). "Objective of the present study was to report on constitutive and CRH- and dexamethasone-regulated POMC, CRH (CRH-R1), and glucocorticoid receptor (NR3C1) gene expression in a large series of human corticotrope adenomas." (PMID 27220856, 2017). "Incubation with CRH brought about an increase in POMC in the majority of adenomatous specimens, in agreement with studies on some 10 ACTH-secreting adenomas." (PMID 27220856, 2017). "Of the three “silent” adenomas, tumor 1, a silent GH adenoma, responded predominantly to GHRH and to a lesser extent to GnRH and TRH, whereas tumor 13, a silent ACTH adenoma, responded similarly to GHRH, CRH, TRH, and TRH/DA." (PMID 38612778, 2024). "Nevertheless, BIPSS has pitfalls which can lead to false-negative results (e.g., catheter malposition, anatomical abnormalities of the inferior petrosal sinus, adenomas unresponsive to CRH) and false-positive results (e.g., IPSS in remission phase of cyclical CS and ectopic CRH production)." (PMID 37560300, 2023). "For both 18F-FDG (± CRH stimulation) and 11C-Met, macroadenoma detection was not better than in adenomas sized 7–9 mm (62% versus 82% and 100% versus 100%), while sensitivity for detection of adenomas ≤6 mm was lower (45% and 83%)." (PMID 37109254, 2023). "Interestingly, the magnitude of POMC increase was not correlated with CRH receptor abundance, a finding which dovetails with data obtained at immunohistochemistry showing that CRH-R1 staining density in adenomas is not proportional to the ACTH response to CRH." (PMID 27220856, 2017).
adenoma (continued). "Thus, results may be biased by specimen selection; indeed, one study reported that adenomas are not responsive to CRH but the same investigators showed that CRH does stimulate ACTH in subsequent experiments." (PMID 27220856, 2017). "BIPSS is performed in patients of ACTH-dependent CS when there are discordant responses to dynamic testing (intravenous CRH stimulation and HDDST (high-dose dexamethasone suppression test)) or pituitary imaging fails to localize adenoma or reveals pituitary tumor with size ≤6 mm." (PMID 29440131, 2018).
Hypertension (15 papers, 2011 to 2026). The presence of chronic increased pressure in the systemic arterial system. "Elevated CRH is a major risk factor for preterm labor, premature rupture of the membranes, and pregnancy-induced hypertension and eclampsia." (PMID 36076160, 2022). "The placenta regulates the maternal immune response and endocrine system by producing CRH, and affects the blood flow and nutrient supply of the placenta, which may lead to placental dysfunction and hypertension." (PMID 39967661, 2025). "The relative preponderance of NPFF (and its receptors) and its intimate anatomical relationship to important cardiovascular regulatory peptides such as corticotropin releasing hormone (CRH) in human hypothalamus suggests an important role for this peptide in hypertension." (PMID 23404625, 2013). "Interestingly, an up-regulation of CRH-secreting cells in the human hypothalamic PVN of patients who suffered from essential hypertension has been reported." (PMID 23404625, 2013). "While multiple regulatory processes in addition to DNA methylation can influence CRH gene expression, it is also possible that IUGR cases utilised in other studies included cases with co-existing hypertension/pre-eclampsia that might have contributed to altered CRH levels." (PMID 23667551, 2013).
Hypoglycemia (15 papers, 2015 to 2026). A decreased concentration of glucose in the blood. "Interestingly, CRH production was found in catecholaminergic brainstem nuclei most probably transmitting systemic stressor information (e.g., blood loss, pain, hypoglycemia) to the PVN." (PMID 40362394, 2025). "Adrenocorticotropin hormone and cortisol responded poorly to both insulin-induced hypoglycemia and CRH administration." (PMID 35281581, 2022). "Dh44 is a homolog of vertebrate CRH, which is released in the hypothalamus in response to external and internal stressors like hypoxia or hypoglycemia." (PMID 34085637, 2021). "The stressors, such as hypoglycemia, induce the release of corticotropin-releasing hormone (CRH) from the paraventricular nucleus (PVN) of the hypothalamus." (PMID 27563309, 2016). "Compared with the control group, CRH transcript expression in the hypothalamus was decreased at adulthood in rats subjected to recurrent hypoglycemia." (PMID 26343738, 2015). "Stressors such as hypoglycemia induce the release of corticotropin-releasing hormone (CRH) from the hypothalamic paraventricular nucleus (PVN)." (PMID 26343738, 2015). "The CRH stimulation test has been suggested as a useful and safe alternative to the ITT, as the cortisol response to CRH has been found to be significantly correlated with cortisol response to insulin-induced hypoglycemia." (PMID 26500680, 2015). "The ACTH-cortisol axis showed a lack of responsiveness in both the corticotropin-releasing hormone (CRH) and insulin-induced hypoglycemia tests, but responded to the continuous ACTH infusion, indicating adrenal cortex functionality but deficient endogenous ACTH secretion." (PMID 40677481, 2025). "CRH stimulation test that has lower standardization and availability and insulin-induced hypoglycemia test which is the gold standard test for AI diagnosis., However, complications have limited insulin-induced hypoglycemia test's applicability." (PMID 34557164, 2021). "Finally, we suggest that future studies consider assessing the HPA axis using expanded and complementary laboratory strategies, such as insulin-mediated hypoglycemia stimulation tests; CRH stimulation tests; or a combination of hair, saliva and/or blood measurements." (PMID 39585074, 2024). "CRH is considered to be the main stimulus driving ACTH release in healthy humans, however, close correlation between these hormones in horses only occurs during times of critical illness such as with profound hypoglycemia." (PMID 37432047, 2023). "Insulin-induced hypoglycemia is considered to act on the hypothalamus, where it strongly stimulates ACTH secretion by inducing the release of both corticotropin-releasing hormone (CRH) and arginine vasopressin (AVP)." (PMID 36494805, 2022). "No additional increase in CRH secretion is seen during hypoglycemia." (PMID 26343738, 2015). "Any ACTH and corticosterone response to hypoglycemia in the neonatal period appears to be mediated by arginine vasopressin (AVP) and not CRH." (PMID 26343738, 2015).
acne (13 papers, 2014 to 2026). An inflammatory process of the sebaceous glands which is characterized by comedones, nodules, papules and/or pustules on the skin. "CRH, for instance, is highly expressed in acne-prone skin, supporting a mechanism for stress-induced acne, and it interacts with androgenetic signaling pathways involved in acne pathogenesis." (PMID 38791344, 2024). "Previous work shows that the level of CRH is increased in acne-involved skin, especially in the sebaceous glands, possibly activating pathways which affect immune and inflammatory processes leading to the development and stress-induced exacerbation of acne." (PMID 37205913, 2023). "For instance, the release of corticotropin-releasing hormone (CRH) from the hypothalamus, which activates the hypothalamic–pituitary–adrenal (HPA) axis, may trigger the formation of acne lesions." (PMID 38392567, 2024). "Corticotropin-releasing hormone (CRH), a neuropeptide, shows significantly stronger expression in sebaceous gland cells of acne-affected skin than in non-affected skin." (PMID 38193084, 2023). "Furthermore, CRH has been investigated as a possible factor in disorders of adnexal skin structures, such as acne vulgaris, but not yet in excessive sweating." (PMID 24647796, 2014).
anxiety disorder (13 papers, 2012 to 2025). A category of psychiatric disorders which are characterized by anxious feelings or fear often accompanied by physical symptoms associated with anxiety. "It is suggested from these studies that children with these SNPs in the CRH gene are less likely to display behavioral inhibition and thus, are at a decreased risk for developing anxiety disorders later in life." (PMID 23077729, 2012). "Understanding these interactions will be essential for comprehensively addressing the role of CRH across vigilance states and its potential implications in anxiety disorders." (PMID 40830097, 2025). "At the same time, the hypersecretion of CRH during ELA can induce long-lasting behavioral and neuroendocrine changes that underlie the later development of anxiety disorders." (PMID 36338879, 2022). "The LC receives a rich CRH innervation contains CRH receptors and is critically involved in the pathophysiology of stress and anxiety disorders." (PMID 32499732, 2020). "Corticotropin-releasing hormone (CRH) regulates the stress-induced activation of the HPA axis and mediates autonomic and behavioural changes associated with anxiety disorders." (PMID 23150170, 2013). "The hyperactive CRH system and HPA axis abnormalities that occur in some patients suggests a potential role for CRH in modulating the neurocircuitry underlying mood and anxiety disorders." (PMID 23077729, 2012). "Thus, CRH neuronal circuits interact with the serotonergic and the noradrenergic systems, which are critically involved in mood and anxiety disorders." (PMID 32499732, 2020).
Cognitive impairment (13 papers, 2016 to 2026). Abnormal cognition is characterized by deficits in thinking, reasoning, or remembering. "In this study, the levels of 5-HT, GABA, and BDNF in the blood of premature rats with cognitive impairment decreased, while that of GR, CRH, IL-6, and TNF-α increased, in comparison to the control group." (PMID 36061856, 2022). "Accumulating evidence suggests that unrestrained secretion of corticotropin-releasing hormone (CRH) can contribute to the apparition of depressive symptoms as well as cognitive deficits (for review)." (PMID 26901205, 2016). "The HPA axis has been implicated in the pathophysiology of multiple emotional and cognitive disorders by data from different neuroscience disciplines, including correcting the abnormal secretion of adrenocorticotropic hormone (ACTH), CORT, and CRH." (PMID 37109699, 2023). "The levels of 5-HT, GABA, and BDNF in the blood samples from the premature rats with cognitive impairment were significantly lower than that from the normal control group, while the serum levels of GR, CRH, IL-6, and TNF-α were significantly up-regulated in rats with cognitive problem." (PMID 36061856, 2022). "Furthermore, cognitive impairment caused significantly decreased levels of 5-HT, GABA, and BDNF, and increased levels of GR, CRH, IL-6, and TNF-α in rat blood." (PMID 36061856, 2022). "Furthermore, we found that the cognitive disorder and altered intestinal microflora structure in preterm rats were associated with decreased levels of 5-HT, GABA, and BDNF, and increased levels of GR, CRH, IL-6, and TNF-α in serum." (PMID 36061856, 2022). "Intracerebroventricular injection of corticotropin-releasing hormone in mice increased pMAPK1 in hippocampal CA1-CA3 areas, while it reduced pMAPK (P38 and ERK) levels in rats which improved cognitive impairment." (PMID 38047157, 2023). "We then compared the serum levels of soluble factors including 5-HT, GABA, BDNF, GR, CRH, IL-6 and TNF-α in preterm rats from the normal control group and cognitive impairment group." (PMID 36061856, 2022). "CRH was also decreased in αSyn positive Lewy body disease compared with αSyn negative non-PS (P = 2e−03) and correlated with cognitive impairment and inflammation in αSyn positive Lewy body disease." (PMID 39605973, 2024). "This study aimed to review the evidence of the variation in CSF levels of CRH, ACTH, and cortisol in subjects with mild cognitive impairment (MCI) and AD compared with subjects without cognitive disorders." (PMID 38089172, 2023). "Therefore, the present study is a systematic review aiming to compile the literature on the variation in CSF levels of CRH, ACTH, and cortisol in subjects with mild cognitive impairment (MCI) and AD compared with subjects without cognitive disorders." (PMID 38089172, 2023).